RBFOX1 (RNA binding fox-1 homolog 1)
Description:
RNA-binding protein that regulates alternative splicing events by binding to 5'-UGCAUGU-3' elements. Regulates alternative splicing of tissue-specific exons and of differentially spliced exons during erythropoiesis.
Synonyms: A2BP1; FOX1; HRNBP1; FOX-1; 2BP1
Tractability: PROTAC: ubiquitination databases record sites on it.
Gene: Protein-coding gene on chromosome 16 (5,239,802 to 7,713,340, forward strand). Ensembl gene ENSG00000078328.
Subcellular location: Nucleus; Cytoplasm
Subcellular location (Human Protein Atlas): Nucleoplasm; Cytosol; Golgi apparatus; Nucleoli fibrillar center
Gene Ontology:
Molecular function: protein binding; mRNA binding; RNA binding; nucleic acid binding
Biological process: nervous system development; regulation of alternative mRNA splicing, via spliceosome; RNA transport; regulation of RNA splicing
Cellular component: cytoplasm; cytoplasmic stress granule; nuclear stress granule; nucleoplasm; trans-Golgi network; nucleus
Genetic constraint (gnomAD): Loss-of-function variants: 8 observed, 46.35 expected, observed/expected ratio (o/e) 0.17, 90% interval 0.1 to 0.31. The synonymous counts are far from expectation, so gnomAD's model fits this gene poorly and the ratio says little. Missense variants: 588 observed, 503.53 expected, observed/expected ratio (o/e) 1.17, 90% interval 1.09 to 1.25. Synonymous variants: 311 observed, 212.71 expected, observed/expected ratio (o/e) 1.46, 90% interval 1.33 to 1.61.
Homologues: Orthologues: pig RBFOX1 (98% identical), mouse Rbfox1 (98% identical), rat Rbfox1 (98% identical), guinea pig RBFOX1 (94% identical), chimpanzee RBFOX1 (86% identical), dog RBFOX1 (85% identical), tropical clawed frog rbfox1 (84% identical), macaque RBFOX1 (82% identical), zebrafish rbfox1 (81% identical), rabbit RBFOX1 (76% identical), Drosophila melanogaster Rbfox1 (45% identical), Caenorhabditis elegans fox-1 (35% identical). Paralogues in human: RBFOX2 (64% identical), RBFOX3 (60% identical).
Diseases named in the same sentence as RBFOX1 in open-access papers:
RBFOX1 is named in the same sentence as 129 diseases in open-access papers, as found by Europe PMC text mining. Sharing a sentence is not in itself a finding about the gene and the disease. The quoted sentences say what the papers report.
autism (33 papers, 2009 to 2024). Persistent deficits in social interaction and communication and interaction as well as a markedly restricted repertoire of activity and interest as well as repetitive patterns of behavior. "RBFOX1 haploinsufficiency causes neurodevelopmental phenotypes including autism, intellectual disability, and epilepsy." (PMID 39654053, 2024). "Dysregulation of RBFOX1 has been implicated in various neurodevelopmental conditions, such as autism, intellectual disability and epilepsy." (PMID 38245794, 2024). "The three genes affected by PAE in both brain and the liver tissues were the Autism Susceptibility Gene 2 (Auts2), Androglobin (Adgb), and RNA Binding Protein Fox 1 (Rbfox1) genes." (PMID 39239947, 2024). "The spliced genes mediated by the RNA-binding protein RBFOX1 regulate neuronal development and are associated with developmental disorders such as autism." (PMID 35085775, 2022). "The RBFOX1 gene has repeatedly been linked to epilepsy, with the earliest reports based on de novo structural gene variants observed in patients comorbid for autism, intellectual disability, or pontocerebellar hypoplasia." (PMID 34490042, 2021). "Deletion, mutation, and translocation in the Rbfox1 gene were found in individuals with mental retardation, epilepsy, autism, and development delay." (PMID 34599184, 2021). "Twenty nine genes were preferentially edited in excitatory neurons, and 43 genes were edited more heavily in inhibitory neurons, including RBFOX1, its target genes, and genes in the autism-associated Prader–Willi locus (15q11)." (PMID 34535545, 2021). "RBFOX1 is implicated in autism, epilepsy syndromes, and Alzheimer’s disease and plays an important role in mammalian brain development." (PMID 32576137, 2020). "We found that upregulation of Rbfox1, an RNA binding protein associated with intellectual disability, epilepsy and autism, increases selectively hippocampal TrkB.T1 isoform expression." (PMID 31429825, 2019). "Genomic mutations affecting RBFOX1 expression have been associated with intellectual disability, epilepsy, autism and Parkinson’s disease." (PMID 31429825, 2019). "The 16p13.3 region and the RBFOX1 gene have been implicated in autism; FOXO1 is a transcription factor; and ST6GALNAC3 is expressed in the reproductive tract." (PMID 29434669, 2018). "In humans, reduced RBFOX1 expression has been associated with autism, epilepsy and heart disease although the mechanistic relationship between RBFOX1 downregulation and these disorders is still unknown." (PMID 31429825, 2019). "Moreover, RBFOX1 dysregulation has been associated with intellectual disability, autism, epilepsy and Parkinson disease, pathologies that have been associated with alterations in BDNF signaling as well." (PMID 31429825, 2019). "One of these loci, RBFOX1, is an RNA-binding protein associated with autism." (PMID 27539784, 2016). "Furthermore, rare copy number abnormalities of RBFOX1 have been reported for patients with neurological diseases like epilepsy, mental retardation and autism strongly indicating that partial RBFOX1 deletions are a recurrent risk factor of neurodevelopmental defects in human." (PMID 24039908, 2013). "Genome-wide mapping has shown that RBFOX1, RBFOX2, and RBFOX3 directly control the splicing of genes that are upregulated during brain development and whose dysregulation is linked to autism." (PMID 39764514, 2024). "These included the regions harboring known autism risk genes, CSMD1, NRXN2, and RBFOX1, all of which were found to be hypomethylated in both discovery and validation analyses." (PMID 36035158, 2022). "A female with autism carrying a 5′-terminal microdeletion of RBFOX1 due to a de novo translocation t(15p;16p) displayed a significantly reduced RBFOX1 mRNA expression in lymphocytes." (PMID 24039908, 2013). "Copy number variations of CHRNA7 and RBFOX1 have been reported in patients with mental retardation, autism and schizophrenia or seizure." (PMID 22487416, 2012).
autism (continued). "Moreover, RBFOX1 expression is reduced in the post-mortem brains of individuals with autism, correlating with splicing irregularities in genes critical for synaptogenesis." (PMID 39764514, 2024). "RBFOX1 (RNA binding protein fox-1) regulates alternative splicing in tissue-specific exons, and its cytoplasmic target mRNAs are enriched in genes involved in cortical development and autism." (PMID 33218114, 2020). "Several candidate autism susceptibility genes were hypermethylated (P <0.05) in the HMFA, including Shank3, Cacana1g, Gtf2i, Rapgef4, and Nbea in male offspring and Ext1, Ube3a, Erbb4, Grip1, Grm8, Reeln, Shank3, and Rbfox1 in female offspring." (PMID 24484737, 2014). "Rare copy number abnormalities of RBFOX1 have also been associated with mental retardation in comorbidity with and without seizures, attention deficit disorder and autism." (PMID 24039908, 2013). "Abnormal reduction of Rbfox1/2 (A2BP1) was reported in a subset of ASD patients and copy number variation (CNV) analysis disrupting A2BP1 (or Rbfox1) have been reported in patients with autism, schizophrenia, epilepsy and mental retardation." (PMID 35013113, 2022).
epilepsy (28 papers, 2013 to 2025). A brain disorder characterized by episodes of abnormally increased neuronal discharge resulting in transient episodes of sensory or motor neurological dysfunction, or psychic dysfunction. "Some of these variants are found in genes relevant to ASD and epilepsy, including RBFOX1, DLGAP2 and TAOK2." (PMID 38283851, 2024). "It is also possible that the RBFOX1 deletion is associated with an increased risk of seizure disorder with variable expressivity." (PMID 37033539, 2023). "Dysregulation of RBFOX1 has been linked to intellectual disability, autism, epilepsy and Parkinson’s disease (PD) pathologies that are shared with dysregulation of brain-derived neurotrophic factor (BDNF) signaling." (PMID 38596700, 2022). "Copy number variations (CNVs) in the RBFOX1 gene are associated with various neurodevelopmental disorders such as epilepsy, intellectual disability (ID) and ASD." (PMID 32431595, 2020). "Rbfox1 is a splicing regulator that has been associated with various neurological conditions such as autism spectrum disorder, mental retardation, epilepsy, attention-deficit/hyperactivity disorder and schizophrenia." (PMID 30001398, 2018). "Some well known Rbfox1 target transcripts which have been directly linked to epilepsy were also investigated." (PMID 25571999, 2015). "Mutations in RNA-binding Fox 1 (RBFOX1) are known to be associated with neurodevelopmental disorders including epilepsy, mental retardation and autism spectrum disorder." (PMID 25571999, 2015). "RBFOX1 mutations have been identified in genetic focal and generalized epilepsies in humans and may act as a susceptibility gene in both humans and baboons." (PMID 35909685, 2022). "This preliminary study highlights the potential role of RBFOX1 in the epileptic baboon, a protein involved in transcriptomic regulation of multiple epilepsy candidate genes in humans and itself previously implicated in human epilepsy, both focal and generalized." (PMID 34490042, 2021). "Previous studies have suggested that mutations in RBFOX1 are related to epilepsy." (PMID 25571999, 2015). "However, other studies have revealed mutations or the downregulation of RBFOX1 in specimens obtained from patients with epilepsy or malformations of cortical development (MCD)." (PMID 25571999, 2015). "Changes in RBFOX1 have been related to several neurodevelopmental syndromes, including ID, epilepsy, and ASD42–44, with important roles in neuronal migration and synapse network formation during corticogenesis." (PMID 31780800, 2019). "We demonstrated that RBFOX1 protein is upregulated in cortical lesions obtained from patients with epilepsy/MCD." (PMID 25571999, 2015). "A significantly stronger RBFOX1 staining signal was observed in the cortical lesions of the patients with MCD/epilepsy compared to the controls." (PMID 25571999, 2015). "Once we established this causal relationship between the altered Rbfox1 protein expression and neuronal hyperexcitation, we then wished to determine whether this increase in excitability results from changes in certain known Rbfox1 target transcripts that have been directly linked to epilepsy." (PMID 25571999, 2015). "Mutations in RBFOX1 [also known as ataxin 2-binding protein 1 (A2BP1)] have been observed in a growing number of neurodevelopmental disorders, including epilepsy, mental retardation and autism spectrum disorder." (PMID 25571999, 2015). "In clinical settings, variations within the RBFOX1 gene have been shown to be associated with autism spectrum disorder (ASD), schizophrenia, epilepsy and attention deficit hyperactivity disorder (ADHD)." (PMID 26274327, 2015). "We analyzed the expression of RBFOX1 in brain tissues obtained from patients with epilepsy/MCD and control subjects." (PMID 25571999, 2015). "Defects in RBFOX1 have been implicated in many neurodevelopmental and neuropsychiatric disorders including ASD, bipolar disorder, schizophrenia, attention-deficit hyperactivity disorder and epilepsy." (PMID 38596700, 2022).
epilepsy (continued). "In this study, we provided new evidence to support the hypothesis that abnormally expressed RBFOX1 is related to epilepsy/MCD by analyzing the expression of RBFOX1 in the epileptogenic zone." (PMID 25571999, 2015). "Mutations in RBFOX1 have been observed in epilepsy or mental retardation, although brain tissues were not available in these studies." (PMID 25571999, 2015). "We suspected that the overexpression of RBFOX1 in the epileptogenic zone may contribute to epilepsy." (PMID 25571999, 2015). "Clinical studies have revealed mutations or the downregulation of RBFOX1 in the specimens obtained from patients with epilepsy or MCD; specifically, the specimens were not from the actual epileptogenic lesions." (PMID 25571999, 2015). "Thus, the increased protein level of RBFOX1 in the brain tissues of patients with epilepsy/MCD is a significant finding and worthy of further study." (PMID 25571999, 2015). "Accordingly, A2BP1 codes for a RNA-binding protein, Rbfox1, that regulates the alternative splicing of neuronal transcripts involved in synaptic transmission and membrane excitation, some of which involved in epilepsy." (PMID 24278214, 2013). "By electrophysiological recordings analysis, we found that cultured rat cortical neurons with an increased Rbfox1 expression were hyperexcitated, which provides direct evidence to support the hypothesis that Rbfox1 may contribute to neuronal hyperexcitation and epilepsy." (PMID 25571999, 2015). "Interestingly, NOVA interacts functionally with Rbfox1, and many of the proteins showing large Nova-dependent changes are also involved in synaptic regulation with links to epilepsy were also found to have NOVA-dependent NMD exons regulated after induction of seizures in mice." (PMID 23359859, 2013). "In humans, CNVs that are located in different parts of the 5’-region of the RBFOX1 gene have been found in patients with ID, ASD, ADHD, epilepsy, and schizophrenia." (PMID 32431595, 2020). "Thus, it is necessary to re-examine the expression of RBFOX1 in cortical lesions from patients with MCD and epilepsy." (PMID 25571999, 2015). "Based on these data, we concluded that the increased Rbfox1 protein expression may be the cause of hyperexcitation in cultured cortical neurons, and the increased RBFOX1 protein epxression is likely the cause of epilepsy in human patients rather than a symptom of the epilepsy." (PMID 25571999, 2015).
schizophrenia (26 papers, 2012 to 2025). A major psychotic disorder characterized by abnormalities in the perception or expression of reality. "In contrast, a more limited enrichment was found for “Schizophrenia symptom severity measurement” (p = 0.0003), with only three genes displaying significant associations (RBFOX1, CSMD1, and TENM2)." (PMID 39237719, 2025). "In this study, we report that schizophrenia is associated with lower protein levels of cytoplasmic Rbfox1 isoform in PVIs in PFC of schizophrenia." (PMID 37398467, 2023). "Together, our findings suggest that the Rbfox1-Vamp1 pathway in PVIs is impaired in schizophrenia and that this alteration likely contributes to deficient PFC gamma power in the illness." (PMID 37398467, 2023). "Our combined findings from postmortem studies and computational modeling suggest that alterations of the Rbfox1-Vamp1 pathway in PVIs are a critical component of pathogenic mechanisms underlying deficient PFC gamma oscillations in schizophrenia." (PMID 37398467, 2023). "Mining existing data from large-scale studies of human common genetic variants, we confirmed gene-based and genome-wide association of RBFOX1 with risk tolerance, major depressive disorder and schizophrenia." (PMID 35948661, 2022). "To investigate whether schizophrenia is associated with altered levels of cytoplasmic Rbfox1 in PVIs, we quantified the protein levels of cytoplasmic Rbfox1 in PVIs from the PFC of 20 pairs of schizophrenia and unaffected comparison subjects." (PMID 37398467, 2023). "Prior studies have suggested that alterations in the Rbfox1 pathway could be associated with schizophrenia." (PMID 37398467, 2023). "Furthermore, our simulations predict that these alterations in the Rbfox1-Vamp1 pathway in PVIs are critical components of pathogenic mechanisms underlying deficient PFC gamma oscillation power in schizophrenia." (PMID 37398467, 2023). "In conclusion, our study demonstrates that schizophrenia is associated with lower levels of cytoplasmic Rbfox1 isoform in prefrontal PVIs which could account for lower Vamp1 mRNA levels in the same neurons." (PMID 37398467, 2023). "Here, we tested the hypothesis that schizophrenia is associated with lower levels of cytoplasmic isoform of Rbfox1 protein and its target transcript Vamp1 in prefrontal PVIs." (PMID 37398467, 2023). "Given the well-established role of RBFOX1 in neuronal alternative splicing programs, this result suggests that genetic risk factors for schizophrenia may regulate the master regulators of alternative splicing that leads to dysregulation of isoform networks." (PMID 34356078, 2021). "We show that ZNF804A is a nuclear protein that interacts with neuronal RNA splicing factors and RNA-binding proteins including RBFOX1, which is also associated with schizophrenia, CELF3/4, components of the ubiquitin-proteasome system and the ZNF804A paralog, GPATCH8." (PMID 30597088, 2019). "In a subset of this cohort, Vamp1 mRNA levels in PVIs were also significantly lower in schizophrenia and were predicted by lower cytoplasmic Rbfox1 protein levels across individual PVIs." (PMID 37398467, 2023). "To explore the functional consequence of Rbfox1-Vamp1 alterations in schizophrenia, we simulated the effect of reduced release probability of GABA from PVIs (RPI◊E) on gamma power in a model network of pyramidal neurons and PVIs." (PMID 37398467, 2023). "Our study is limited in assessing the effect of antipsychotics on Rbfox1 levels since all but one of the schizophrenia subjects used in this study were on antipsychotics at the time of death." (PMID 37398467, 2023). "Consistent with this idea, our study shows a positive correlation between the protein levels of cytoplasmic Rbfox1 and the mRNA levels of Vamp1 in PVIs, which are both lower in schizophrenia." (PMID 37398467, 2023).